OGT (O-linked N-acetylglucosamine (GlcNAc) transferase)
Diseases named in the same sentence as OGT in open-access papers (continued):
Sharing a sentence is not in itself a finding about the gene and the disease.
breast carcinoma (continued). "OGT-mediated O-GlcNAcylation of EZH2 attenuates EZH2 ubiquitination in breast cancer cell; PCAF-mediated EZH2-K348 acetylation inhibits CDK1 catalyzing pT345-EZH2 and pT487-EZH2 and increases EZH2 stability in lung cancer." (PMID 33308321, 2020). "In conclusion, we have established that OGT inhibition has a differential effect on breast cancer cells of different phenotypes, with TNBC cells having a particularly high sensitivity." (PMID 30952976, 2019). "This was apparent from a decrease in phosphorylation of PS6, indicating that p-PS6 level can serve as a biomarker of response to OGT inhibition in breast cancer cells." (PMID 30952976, 2019). "More comprehensive breast cancer models are required to unravel the response to inhibition of OGT, and determine its usefulness for the treatment of TNBC." (PMID 30952976, 2019). "In breast cancer, expression of the enzyme that catalyzes O-GlcNAcylation – O-GlcNAc-transferase (OGT), and the extent of protein O-GlcNAcylation, are upregulated in tumor tissue, and correlate with cancer progression." (PMID 30952976, 2019). "To better understand the consequences of OGT inhibition in breast cancer cells, we compared the immediate effects on the proteome of the TNBC cells (MDA-MB-231) and the receptor-positive cells (MCF7)." (PMID 30952976, 2019). "Conversely, reducing OGT levels or O-GlcNAcylation in breast cancer cells leads to inhibition of mTOR activity as measured by phosphorylation of ribosomal protein S6 kinase beta-1 (p70S6K), an mTOR target." (PMID 31272438, 2019). "Here, we set out to compare the impact of OGT inhibition on proliferation and survival of breast cancer cells of different subtypes." (PMID 30952976, 2019). "Here we compare the impact of OGT inhibition on a panel of breast cancer cells with a different hormone receptor status: ER- and PR-positive MCF7 and T47D; and receptor-negative MDA-MB-231, BT-549, MDA-MB-468, HCC38 and HCC70." (PMID 30952976, 2019). "HCF-1 or OGT knockdown in a breast cancer cell line, MDA-MB231 cells, also abolished the MG132-induced elevation of NRF1 protein levels, which were not necessarily correlated with NRF1 mRNA levels." (PMID 29941490, 2018). "On the other hand, increased expression of OGT results in Akt activation in breast cancer cells, leading to enhanced cell proliferation and inhibition of the apoptosis." (PMID 30515357, 2018). "In the future, more OGT inhibitors can be tested using this model to better understand their efficacy for treatment of diabetes and breast cancer." (PMID 30515357, 2018). "In breast cancer cell lines the positive regulation of OGT expression through mTOR is dependent on c-Myc-induced heat shock protein 90A (HSP90A) transcription." (PMID 30356686, 2018). "In this study, we used Petri nets (PNs) to model and investigate the role of PI3K and OGT pathways, acting as key players in crosstalk between diabetes and breast cancer, resulting in progression of these chronic diseases." (PMID 30515357, 2018). "The analysis proposed two combination therapies to combat breast cancer progression in diabetic patients including combination of OGTmRNA silencing and OGT inhibitor (BZX) as first combination and BZX and Metformin as the second." (PMID 30515357, 2018). "For example, breast cancer cells have increased-O-GlcNAcylation and OGT levels, and a reduction of OGT expression correlated to tumor growth decrease." (PMID 27252680, 2016). "Increased protein O-GlcNAcylation and changes in OGT expression have been described in breast cancer, lung cancer, prostate cancer, pancreatic cancer, and colorectal cancer." (PMID 26161361, 2015). "Conversely, reduction of O-GlcNAcylation through RNA interference of OGT in breast cancer cells led to inhibition of tumor growth both in vitro and in vivo." (PMID 25426101, 2014).
breast carcinoma (continued). "We identified downregulated CARs in vicinity or overlapping the oncogenes IGF1R, MYLK, the breast cancer drug target OGT (O-GlcNAc transferase), and the breast cancer-related cyclin CCNL1." (PMID 25264628, 2014). "Reginato’s group first demonstrated negative regulation of MMP2 expression upon OGT inhibition using OGT shRNA in breast cancer cells (an effect probably mediated by down-regulation of FOXM1 protein), associated with decreased cell invasiveness." (PMID 23964270, 2013). "These authors showed that high levels of OGT are responsible for the increased activity of FOXM1 in breast cancer MCF-10A cells overexpressing the activated form of ErbB2." (PMID 23964270, 2013). "In breast cancer 4T1 cells, E-cadherin protein expression was increased by OGT shRNA, while it was decreased by treatment with the pharmacological OGA inhibitors PUGNAc and NButGT." (PMID 23964270, 2013). "Mice injected with breast cancer cells displayed a reduced tumor growth when the injected cells contained OGT shRNA." (PMID 23554695, 2011). "In breast cancer tissue and cells, it was shown that O-glycosylation is increased by increased OGT protein expression." (PMID 23554695, 2011). "However, reducing GATAD2B levels in breast cancer cells significantly reduced the OGT-mediated increase in mammosphere formation in MDA-MB-231 and SUM159 cells." (PMID 40136647, 2025). "Elevated levels of OGT and O-GlcNAc in breast cancer promote breast tumor growth and metastasis." (PMID 40136647, 2025). "In breast cancer, the function and maintenance of CSCs are influenced by protein O-GlcNAcylation and the enzyme responsible for this post-translational modification, O-GlcNAc transferase (OGT)." (PMID 40136647, 2025). "However, the mechanism of CSCs regulation by OGT and O-GlcNAc cycling in breast cancer is still unclear." (PMID 40136647, 2025). "Increased OGT and O-GlcNAc are elevated in various cancers, including breast cancer." (PMID 40136647, 2025). "Using high-throughput combinatorial drug screening and genomic sequencing, we find that the microphthalmia-associated transcription factor (MITF) is activated via O-GlcNAcylation by O-GlcNAc transferase (OGT) in palbociclib-resistant breast cancer cells and tumors." (PMID 38961064, 2024). "Non-coding RNAs also regulate breast cancer progression by altering OGT expression." (PMID 39285476, 2024). "As expected, overexpression of KLF8 increased OGT and O-GlcNAc levels in breast cancer cells." (PMID 37152043, 2023). "OGT expression has been shown to be upregulated by c-MYC in breast cancer cells." (PMID 37152043, 2023). "Genetic inhibition of OGT in breast cancer cells significantly reduces metastasis in mice models." (PMID 37838167, 2023). "Similarly, breast cancer cells with inhibited OGT expression show a reduction in phosphorylation of ERK, which leads to a reduction in expression of pro-proliferation protein Forkhead Box M1 (FoxM1)." (PMID 37838167, 2023). "However, key effects of OGT have been observed in breast cancers including activation of the oncogenic transcription factors FoxM1 and a strong overexpression in breast cancer stem-like cells." (PMID 37231419, 2023). "The critical role of OGT/O-GlcNAc in repairing DNA double-strand break is also observed in breast cancer, where an increase in O-GlcNAc level induces resistance of xenograft tumor against radiation, while inhibition of OGT impairs double-strand break repair and reduces cancer cell growth in vivo." (PMID 37838167, 2023). "Recently, we observed increased levels of KLF8 in CSCs-enriched mammospheres, and increased OGT/O-GlcNAcylation upregulated KLF8 level in breast cancer cells, both in vitro and in vivo, suggesting a potential role of KLF8 in regulating CSCs properties in breast cancer cells." (PMID 37152043, 2023). "Indeed, our OGT analysis of The Cancer Genome Atlas breast cancer subtype dataset revealed that TNBC patients have higher OGT levels than other subtypes of breast cancer." (PMID 37231419, 2023).
breast carcinoma (continued). "Moreover, treatment with OGT inhibitor OSMI-1 suppressed WT MORC2-mediated breast cancer cell migration and invasion." (PMID 34974534, 2022). "The role of OGT in the regulation of cancer-stemness and tumor metastasis, as seen in breast cancer, may potentially be targeted to overcome resistance to chemotherapy." (PMID 34771527, 2021). "In this study, we used OSMI-1 to probe the importance of OGT activity for the survival of tamoxifen-resistant breast cancer cells in an isogenic cell line pair: Tamoxifen sensitive ERα-positive MCF7 cell line (TamS), and its tamoxifen-resistant derivative (TamR)." (PMID 33046784, 2020). "O-GlcNAc transferase (OGT) has emerged as a candidate drug target in breast cancer." (PMID 33046784, 2020). "A recent study reported that the inhibition of OGT expression and activity in breast cancer cell lines could induce SIRT1 stability." (PMID 31717261, 2019). "In breast cancer cells, targeting OGT may reverse the Warburg effect as it decreases glycolytic metabolites and metabolites produced by the PPP while increasing tricarboxylic acid (TCA) metabolites." (PMID 31272438, 2019). "OGT also modifies p120 and β-catenin, which directly bind E-cadherin and dictate its cell surface distribution and might therefore play a role in breast cancer metastasis." (PMID 31272438, 2019). "Similarly, the inhibition of OGT expression and activity in breast cancer cell lines increased SIRT1." (PMID 31717261, 2019). "Moreover, the combination therapy for breast cancer patients consisting of anti-diabetic drugs such as Metformin along with OGT inhibitors, for example BZX, can produce better treatment regimens." (PMID 30515357, 2018). "While in prostate cancer and breast cancer cells, the OGT/O-GlcNAcylation-mediated stabilization of c-MYC is tightly associated with the cell growth, suggesting the possibility of c-MYC as a potential upstream regulator of OGT target genes." (PMID 30082668, 2018). "Similarly, in 3D cultures of T4-2 breast cancer cells, OGT inhibition or silencing suppresses AKT signaling and glycolytic activity." (PMID 30356686, 2018). "In that sense, OGT promotes breast cancer cells invasion in a cofilin-dependent manner." (PMID 27252680, 2016). "However it is worth noting that previous studies have shown that in many oncogenes and tumor suppressors, OGT and O-GlcNAc levels are elevated and that O-GlcNAcylation plays a role in breast cancer metastasis." (PMID 26670328, 2015). "In human breast cancer cells, high level of HIF-α is associated with elevated OGT level." (PMID 25250015, 2014). "KLF8 and OGT may serve as promising targets to overcome challenges in treating breast cancer." (PMID 37152043, 2023). "Notably, OGT’s nutrient sensing role has been previously linked with breast cancer tumorigenesis via the transcription factor FoxM1, but since FoxM1 is not an OGT substrate there remains a missing link in this connection." (PMID 37231419, 2023). "Interestingly, KLF8 and OGT coregulate each other and may form a feed-forward loop in breast cancer cells." (PMID 37152043, 2023). "Also, between breast cancer subtypes, OGT inhibition is most effective in TNBC." (PMID 37231419, 2023). "Besides, OGT can increase SIRT1 protein level in breast cancer." (PMID 35201498, 2021). "In addition, a feed forward loop may exist between c-Myc and OGT as OGT protein levels are regulated in breast cancer cells by c-Myc." (PMID 31272438, 2019). "In addition, OGT silencing inhibits tumor growth in different models including breast cancer, prostate cancer, and pancreatic cancer, indicating that O-GlcNAcylation is important for tumorigenesis and suggesting that OGT represents a novel therapeutic target for these types of cancers." (PMID 26161361, 2015). "Together, these data suggests that OGT and O-GlcNAc protects GATAD2B from proteasome-dependent degradation mediated by the E3 ligase ITCH and also identifies ITCH as a regulator of breast cancer stem cell functions." (PMID 40136647, 2025).
breast carcinoma (continued). "Among them, OSMI‐1, a newly discovered small molecule OGT inhibitor, activates the tumour suppressor ERRFI1 through epigenetic mechanisms, thereby inhibiting breast cancer growth." (PMID 39358921, 2024). "OGT promotes the stability of MEK2 through O-GlcNAcylation at Thr13, thereby enhancing the proliferation and migration of breast cancer cells." (PMID 39285476, 2024). "One study showed that the expression of OGT and elevated levels of HIF-1α are correlated with poor patient outcomes in breast cancers." (PMID 38732122, 2024). "Inhibition of OGT by miR-24 reduces the stability of forkhead box protein A1 (FOXA1), thereby inhibiting breast cancer cell invasion." (PMID 39285476, 2024). "In breast cancer cells, elevated mTOR/c-MYC was previously shown to increase the expression of OGT and O-GlcNAcylation." (PMID 39388284, 2024). "In this study, we have discovered a OGT-MITF axis that plays a crucial role in regulating MITF transcriptional activity and conferring resistance to CDK4/6 inhibitors in breast cancer." (PMID 38961064, 2024). "In breast cancer, MEK2 is directly modified by OGT at Threonine residue 13, which enhances MEK2 phosphorylation and ERK1/2 activation driving cancer cell proliferation." (PMID 37838167, 2023). "In breast cancer, increased OGT expression results in increased levels of pro-EMT proteins, such as vimentin and fibronectin, while genetic inhibition of OGT decreases the expression of these pro-EMT factors." (PMID 37838167, 2023). "Recently, the nutrient sensor O-GlcNAc transferase (OGT) and O-GlcNAcylation was shown to be enriched in CSC populations, where it promotes the stemness and tumorigenesis of breast cancer cells in vitro and in vivo." (PMID 37152043, 2023). "Between subtypes of breast cancer patient tumors, TNBC/basal tumors showed significantly higher OGT expression than estrogen/progesterone receptor-expressing luminal A/B breast tumors." (PMID 37231419, 2023). "In this study, we have discovered a novel OGT-MITF-mediated pathway that plays a crucial role in regulating MITF transcriptional activity and conferring resistance to CDK4/6 inhibitors in breast cancer." (PMID 37886470, 2023). "OSMI-1, an OGT inhibitor, significantly suppresses MORC2-mediated breast cancer cell invasion and metastasis." (PMID 34974534, 2022). "A study in breast cancer cells detected that MTA1, a highly deregulated oncogene involved in the stress adaptation of cancer, is an OGT substrate." (PMID 36291918, 2022). "Intriguingly, datasets deposited in The Cancer Genome Atlas (TCGA) revealed a positive correlation between proteasome subunit expression levels and OGT levels, which is regarded as an NRF1 activator, in breast cancer cases." (PMID 33535386, 2021). "Consistent with OGT’s effects on EZH2, OGT knockdown decreases cellular H3K27 tri-methylation and re-activates a group of EZH2-targeted tumor suppressor genes in breast cancer cells." (PMID 35201498, 2021). "In breast cancer cells, the PI3K–mTOR–MYC signaling pathway is required for elevation of OGT and O-GlcNAcylation." (PMID 33801653, 2021). "Supporting this interpretation, a significant correlation between OGT, an NRF1 activator, and proteasome subunit genes was observed in clinical breast cancer specimens." (PMID 33535386, 2021). "This study showed that HCT116 colon cells stably overexpressing XIAP WT displayed greater changes in OGT and O-GlcNAc modification levels than A549 lung cancer cells and MDA-MB231 breast cancer cells." (PMID 32994395, 2020). "Our findings suggest a link between OGT and ERRFI1 signaling, pointing to OGT as a possible therapeutic target in a significant subset of breast cancer patients." (PMID 33046784, 2020). "We tested two predicted OCN pairs in each cancer type, including NCSTN and DNM1, and NCSTN and OGT in liver cancer; CCNA2 and PTP4A1, and HIF1A and PARP1 in lung cancer; and CCNA2 and PTP4A1, and PLK1 and PTP4A1 in breast cancer." (PMID 31097707, 2019).
breast carcinoma (continued). "This study is not only exhibiting significance of OGT regulation in these diseases but it also helped us to predict that OGT inhibition might reduce cancer cell proliferation and its inhibition in combination to Metformin can reverse breast cancer progression to a significant extent." (PMID 30515357, 2018). "In this study, we determined the impact of OGT on expression of EZH2 target genes FOXA1 and FOXC1, that are involved in breast cancer progression." (PMID 29864144, 2018). "For instance, OGT-mediated O-GlcNAcylation of Ezh2 at Ser75 stabilizes the PCR2 complex, which further promotes histone H3K27 tri-methylation in breast cancer MCF-7 cells." (PMID 28488246, 2017). "Recently, increased O-GlcNAcylation level was found to protect the breast cancer cell line, MCF-7 from tamoxifen induced cell death, whereas siRNA mediated OGT knockdown had opposite effects." (PMID 25426101, 2014). "Importantly, this combination strategy was effective in refractory breast cancer patients, and decreased levels of TYMS and OGT were observed in breast cancer patient specimens collected before and after everolimus-containing treatment." (PMID 41935067, 2026). "OGT regulates the expression of SREBP-1 in a proteasomal and AMP-activated protein kinase (AMPK)-dependent manner, thereby altering lipid metabolism and impacting breast cancer cell survival." (PMID 39285476, 2024). "Despite the fact that OGT expression levels are normally tightly regulated in human cells, our analysis of patient data in The Cancer Genome Atlas (TCGA) found significant elevation of OGT in TNBC tumors over other breast cancer subtypes and non-tumor tissue." (PMID 37231419, 2023). "Interestingly, our study also showed a co-regulation between OGT and KLF8, as KLF8 regulates OGT RNA and protein levels and KLF8 requires OGT for mammosphere formation, suggesting a potential feed-forward loop of OGT and KLF8 to regulate CSCs in breast cancer." (PMID 37152043, 2023). "To confirm that OGT and KLF8 co-regulate each other to promote stem cell properties in breast cancer, we overexpressed KLF8 in TNBC cells and transduced the cells with either control or shRNA targeting OGT, followed by assessing mammosphere formation efficiency." (PMID 37152043, 2023). "Importantly, KLF8 is required for OGT to promote cancer stem-like cells phenotype in breast cancer, and KLF8 and OGT form a feed-forward loop to further induce stem-like cells traits in cancer cells." (PMID 37838167, 2023). "A significant increase in cellular UDP-GlcNAc was found in Nic-treated breast cancer cells, whereas no detectable change in OGT or OGA expression was found, suggesting the potential for an increased the HBP flux." (PMID 31019204, 2019). "Importance of OGT in breast cancer has been previously reported, however the diversity and molecular heterogeneity of breast cancer has never been taken into account." (PMID 30952976, 2019). "In addition, human breast cancers with high HIF-1α and OGT levels, and low OGA levels are correlated with poor patient outcome." (PMID 25426101, 2014). "This suggests that the combined detection of HIF-1α, OGT, and OGA in clinical samples may be useful as potential breast cancer biomarkers." (PMID 25426101, 2014). "To identify proteins regulated by OGT and O-GlcNAc cycling that may contribute to CSC phenotypes, we treated MDA-MB-231 breast cancer cells with an OGA inhibitor Thiamet-G (TMG) to block the removal of the modification and increase the extent of protein O-GlcNAcylation." (PMID 40136647, 2025). "Importantly, knockdown of OGT in KLF8 overexpression reduced mammosphere formation in MDA-MB-231 cells, suggesting both OGT and KLF8 are needed to promote mammosphere formation and stem cell properties of breast cancer cells." (PMID 37152043, 2023).